KDM6B (lysine demethylase 6B)
Diseases named in the same sentence as KDM6B in open-access papers (continued):
Sharing a sentence is not in itself a finding about the gene and the disease.
cancer (continued). "To conclude, it is apparent that the H3K27me3-specific demethylases KDM6A and KDM6B play complex, occasionally contrasting, roles in the pathogenesis of various diseases, ranging from cancer to inflammatory, autoimmune and infectious diseases." (PMID 35915507, 2022). "We found that KDM6B occupies the promoter HIF1α and regulates its expression in matrix-detached cancer cells Hypoxia regulates global transcription in multiple ways, and regulation of the expression and activity of histone demethylases is one of them." (PMID 35186918, 2022). "Lysine (K)-specific demethylase 6B (KDM6B) is an epigenetic enzyme involved in the coordinated control between cellular intrinsic regulators and the tissue microenvironment whereas the pan-cancer analysis of KDM6B remains unavailable." (PMID 35783266, 2022). "Our study highlights an essential role of KDM6B in cancer and has important implications for targeting this protein for anticancer therapies." (PMID 35186918, 2022). "With the TCGA project, we applied the MEXPRESS to explore the possible links of KDM6B and DNA methylation to the differential pathogeneses of cancer." (PMID 35783266, 2022). "KDM6B (Lysine-specific demethylase 6B) is a histone lysine demethyltransferase that plays a key role in many types of cancers." (PMID 36564369, 2022). "We also noticed an increased occupancy of the HIF1α promoter by KDM6B, suggesting its regulatory role in maintaining hypoxia in detached cancer cells." (PMID 35186918, 2022). "Bioinformatics and luciferase reporter assays were used to identify candidate microRNAs of cancer cells responsible for the downregulation of KDM6B." (PMID 34093857, 2021). "The role of KDM6B in cell proliferation and differentiation is regulated by growth factors, cytokines and ligands via distinct signaling pathways in human cancers." (PMID 34950587, 2021). "We further show that miR-138-5p inhibited KDM6B expression and that cancer cell-derived exosomes delivered miR-138-5p to macrophages, leading to the inhibition of the M1 phenotype, while activating M2 polarization." (PMID 34093857, 2021). "Signal transducer and activator of transcription 3 (STAT3) is activated by phosphorylation on receptor-associated Janus kinases (JAKs), and regulates the proliferation and self-renewal ability of cancer stem cells through repression of KDM6B expression." (PMID 34950587, 2021). "We concluded therefore that miR-138-5p mediated the inhibition of KDM6B expression induced by coculture of THP-1 cells with cancer cells." (PMID 34093857, 2021). "Previous researches and our study, which illuminate the antitumoral effect of GSK-J4 by inhibiting KDM6B activity, indicate that a KDM6B-based target therapy is emerging as a promising cancer therapy for various tumors, including PCa." (PMID 33414463, 2021). "Cancer cell-derived exosomal miR-138-5p inhibited M1 polarization and promoted M2 polarization through inhibition of KDM6B expression in macrophages." (PMID 34093857, 2021). "Based on intensive studies across a broad spectrum of tumors, the functional roles of KDM6A and KDM6B were inconsistent in the same type of cancer." (PMID 34950587, 2021). "This suggested that KDM6B regulated the EMT process depending on the cancer type or the stimuli of the microenvironment." (PMID 34165914, 2021). "KDM6B plays a key role in the occurrence and development of various human diseases such as cancer, immune diseases and developmental diseases 15-18." (PMID 33664867, 2021). "Together, these results suggest the exosomal miR-138-5p secreted by cancer cells was delivered to macrophages in which it inhibited KDM6B." (PMID 34093857, 2021). "Although aspects of their biochemical regulation still remain to be determined, demethylase enzymes like KDM6A and KDM6B are often genetically inactivated in various types of cancers." (PMID 33003334, 2020). "Inverse regulation of KDM6A/UTX and the paralogous histone demethylase KDM6B/JMJD3 has been observed in other cancers." (PMID 30987376, 2019).
cancer (continued). "A more recent study showed that treatment of MCF7 and MDA-MB-231 cells with GSKJ4 inhibits self-renewal of cancer stem cells by inhibiting KDM6B and UTX (another histone demethylase) and elevating the global H3K27me3 level." (PMID 30547810, 2018). "Here we report that EZH2 and KDM6B are overexpressed in numerous cancers and involved in the aggressive phenotype and EMT in various cell lines by regulating a specific subset of genes." (PMID 34991274, 2018). "Finally, gene sets enriched exclusively for upregulated genes in untreated KDM6A/KDM6B knockdown cells compared to untreated PLKO.1 cells include several related to cancer (Group 4)." (PMID 39483904, 2024). "Thus, KDM6B plays a crucial and dual role in cancer initiation and progression through binding to promoters of oncogenes or suppressor genes." (PMID 35186918, 2022). "On the contrary, we observed the KDM6B upregulation across 5 of 16 cancer types." (PMID 35783266, 2022). "Moreover, DNA methylation affected the KDM6B expression level as well, which in turn affected its function in cancers." (PMID 35783266, 2022). "Besides, the Human Protein Atlas database allowed us to conduct a pan-cancer study of the KDM6B protein levels." (PMID 35783266, 2022). "Various histone methylases, including KDM6B, regulate normal and cancer stem cells." (PMID 35186918, 2022). "Our work found that KDM6B occupies the promoter of CD44 during matrix detachment of cancer cells." (PMID 35186918, 2022). "However, we firmly believe this is the first report to show epigenetic regulation of CD44 by KDM6B in various concrete cancer types." (PMID 35186918, 2022). "We found that the expression of KDM6B differed in different cancer types and stages." (PMID 35783266, 2022). "Based on the positive association between KDM6B and DNA methyltransferases in various cancers, we assumed that KDM6B may affect the DNA methylation status in tumorigenesis." (PMID 35783266, 2022). "In this work, we observed that KDM6B was down-regulated in 11 of 16 cancer types." (PMID 35783266, 2022). "The KEGG analysis also indicated that the crosstalk of the KDM6B and IL-17 signaling pathways may influence the effects of KDM6B in cancers." (PMID 35783266, 2022). "Therefore, it was valuable to perform a pan‐cancer analysis of the expression difference and potential molecular mechanism of KDM6B across different cancers." (PMID 35783266, 2022). "Interestingly, EZH2, BMI1 and the histone demethylase (HDM) Lysine Demethylase 6B (KDM6B also called JMJD3), which can remove H3K27me3, have been associated with EMT, poor prognosis and metastasis in cancer." (PMID 36135315, 2022). "In addition, the functions of KDM6B in pan-cancers were only tested with the bioinformatics analysis; therefore, in vitro or in vivo experiments should be performed to conduct a more solid conclusion." (PMID 35783266, 2022). "Notably, this led to the identification of three in vitro substrates (MLL1, p300, and KDM6B), which are relevant to the field of cancer progression." (PMID 35625569, 2022). "Our results suggest KDM6B as a critical regulator of metastasis in different cancer types." (PMID 35186918, 2022). "Effects of a low KDM6B expression on clinical outcomes in various cancers." (PMID 35783266, 2022). "Cancer cells resistant to CDK4/6 inhibitor also are resistant to KDM6B inhibition." (PMID 34893606, 2021). "Applying GSK-J4 to inhibit KDM6B could result in the growth inhibition of different cancer cell lines, including T-ALL and glioma." (PMID 33414463, 2021). "All these findings suggest an important role of KDM6B in cancer progression." (PMID 34165914, 2021). "All these findings suggest an important role of KDM6B in the development of cancers." (PMID 34165914, 2021). "Taken together, these data demonstrate that a high E2F gene signature is correlated with GSK-J4 sensitivity, and thus it may serve as a biomarker for effectiveness of KDM6B inhibitors in cancer treatment in the future." (PMID 34893606, 2021).
cancer (continued). "Importantly, distorted H3K27me3 landscape due to alterations in PRC2 subunits and two KDM6 enzymes (KDM6A or UTX, KDM6B or JMJD3) has been observed in the vast majority of human cancers 11-13." (PMID 32929331, 2020). "KDM6B has been described to be differentially expressed between cancer and normal adjacent tissues." (PMID 34991274, 2018). "KDM6B can also modulate cancer aggressiveness in a demethylase-independent manner." (PMID 34991274, 2018). "Therefore, the characterization of the role of EZH2 and KDM6B during EMT should provide new possibilities for designing anti-cancer therapeutic approaches." (PMID 34991274, 2018). "KDM6B was described to modulate the expression of EMT ATFs during EMT in various cancer cell lines." (PMID 34991274, 2018). "Altogether, these data suggested that KDM6B could be correlated, or inversely correlated, with invasion and cancer aggressiveness regarding the cancer model." (PMID 34991274, 2018). "Growing evidence suggests that KDM6B regulates cancer development." (PMID 28947976, 2017). "Among the most important histone demethylases associated with the development of cancer are LSD-1/KDM1A, and members of the Jumonji family JARID1A-1C/KDM5A-5C, JHDM1B/KDM2B, JMJD2C/KDM4C, JMJD2A/KDM4A, JMJD3/KDM6B, and UTX/KDM6A, which will be analyzed in detail in the following paragraphs." (PMID 24280700, 2012). "Furthermore, the role of KDM6B in cancer is complex and controversial." (PMID 40959109, 2025). "In addition, Kdm6b is also involved in maintaining the pluripotency of mouse embryonic stem cells, assisting the self-renewal and differentiation of cardiovascular cells, and skin repairment, immune system, neurodegenerative disease, and cancer." (PMID 34716527, 2023). "Similarly, KDM6B is highly expressed in various cancers and overexpressed KDM6B could promote drug resistance." (PMID 37638338, 2023). "Our goal was to determine how KDM6B influences the clinical outcomes and immune infiltration in certain cancers and recognize the potential pathways to offer a relatively comprehensive understanding of KDM6B’s dual role, which may serve as a new therapeutic target." (PMID 35783266, 2022). "The KDM6B expression level was associated with DNA methyltransferase activity, TMB, MSI, and immune cell infiltration, across various cancer types with different correlations, through which KDM6B may impact on the clinical outcomes and immune therapeutic effects." (PMID 35783266, 2022). "Since KDM6B inhibition appears to affect its antitumor activity through downregulation of the E2F transcriptome, we hypothesized that high levels of the E2F transcriptome may correlate with the response of cancer cells to KDM6B inhibition." (PMID 34893606, 2021). "Therefore, cancer cells with high E2F activity appear to be more sensitive to KDM6B inhibition." (PMID 34893606, 2021). "Kyoto encyclopedia of genes and genomes (KEGG) pathway analysis revealed that differentially expressed genes were significantly enriched in gene sets involved in VEGF signaling, Rap1 signaling and Ras-MAPK signaling, suggesting that KDM6B might have profound impacts on cancer biology." (PMID 33664867, 2021). "Moreover, we observed morphological changes and altered actin cytoskeleton in KDM6B-KD OS cells, such changes might affect epithelial-mesenchymal transition, a critical event that occurs during carcinoma invasion and metastasis." (PMID 33664867, 2021). "We also report that new cancer therapeutic strategies are targeting KDM6B and EZH2, but the specificity of these treatments may be increased by learning more about the mechanisms of action of these enzymes and their specific partners or target genes in different cancer types." (PMID 34991274, 2018).
cancer (continued). "GSK‐J4 is an effective dual inhibitor of H3K27me3/me2 demethylases KDM6B and KDM6A, known to promote gene silencing and cell apoptosis by inhibiting KDM6A to regulate histone methylation levels, with applications in cancer treatment." (PMID 38874525, 2024). "Our data suggest that the rapid and sustained upregulation of KDM6B following matrix detachment is necessary for SOX2 and CD44-mediated stemness to enhance anchorage-independent survival of various cancer patients’ cells." (PMID 35186918, 2022). "KDM6B expression level and the correlation with immune infiltration, TMB, and MSI in various cancers, in which the KDM6B expression level was significantly different from its matched normal tissues." (PMID 35783266, 2022). "With the correlation varying in different tumors, the KDM6B expression level was correlated with TMB in nine cancer types and with MSI in six cancer types, thus affecting the response to immunotherapy." (PMID 35783266, 2022). "Specifically, KDM6B, RGS19, and SMAD3, which belong to beta-catenin binding in the gene ontology, were up-regulated during the process of cancer plasticity." (PMID 35673567, 2022). "Over the past decades, multiple epigenetic regulators have been identified as modulators of the EMT program in various cancer cell lines in 2D, e.g., HDAC, DNMT, LSD1, KDM6B, PRMT5, EZH2, and G9a67–76." (PMID 34253738, 2021). "KDM6B is upregulated via Smad signaling by activated by transforming growth factor-β (TGF-β), and that KDM6B in turn upregulates SNAI1, which is a master transcription factor in epithelial-mesenchymal transition (EMT) and cancer progression." (PMID 34950587, 2021). "Surprisingly, KDM6B, in contrast to KDM6A, acts as an oncogene in NOTCH1 overexpressing T-ALL cancer." (PMID 33003334, 2020). "Based on clinical settings, these results further consolidate the therapeutic rationale targeting KDM6 enzymes in CRC and also pinpoint KDM6B as a potential predictor for recurrence of CRC and other common cancers." (PMID 32929331, 2020). "The epigenetic proteins EZH2 and KDM6B, two enzymes controlling the methylation level of the histone H3 at the position K27 (H3K27), are major components of cancer aggressiveness and EMT." (PMID 33291363, 2020). "This review highlights the paradoxical functions of EZH2 and KDM6B during EMT and cancer aggressiveness." (PMID 34991274, 2018). "The second paradoxical role of EZH2 and KDM6B during EMT and cancer aggressiveness is that they are also inactivated or under-expressed in some cancer types and linked to epithelial phenotypes in other cancer cell lines." (PMID 34991274, 2018). "In these cancers, HPV oncogene expression similarly dysregulates expression of key regulators of H3K27me3, including members of PRC2 and the demethylases KDM6A and KDM6B." (PMID 29069809, 2017). "A mechanistic explanation for the dramatically decreased H3K27me3 levels in HPV16 positive cervical lesions and cancers was provided by the finding that KDM6A and KDM6B are expressed at markedly higher levels in these cells." (PMID 23673719, 2013). "Furthermore, specific demethylation of GATA3 and KDM6B transcripts can increase the expression of SLC7A11, leading to a decrease erastin sensitivity of cancer cells." (PMID 39800682, 2025). "Other candidates, such as SMARCA1, KDM6B, IRF2, PLK4, and HUWE1, may well have functional relevance to cancer development in particular cancer types, and be worthy of further investigation." (PMID 40514689, 2025). "However, some histone demethylases, such as KDM6B (JMJD3), play a dual role in cancer metastasis, highlighting the importance of cellular context." (PMID 40872531, 2025). "The promise for the use of small molecular inhibitors to target UTX/KDM6B and EZH2 enzymes as an anti-fibrotic therapy is provided by the FDA-approved EZH2 inhibitor, tazemetostat, an oral treatment currently being used with cancer patients." (PMID 37476157, 2023).
cancer (continued). "Nevertheless, despite the extensive clinical statistics, there is no available cross-sectional evidence of the correlation of KDM6B and different cancers." (PMID 35783266, 2022). "Furthermore, GSK J4 treatment significantly reduces the occupancy of KDM6B on promoters of both SOX2 and CD44, suggesting the KDM6B-driven regulation of these stemness genes in detached cancer cells." (PMID 35186918, 2022). "Moreover, like KDM6A, KDM6B interacts with ER or RAR in the presence of estrogens or retinoic acid, and regulates the proliferation and differentiation of cancer cells." (PMID 34950587, 2021). "Whereas enzymatic roles of KDM6A and KDM6B are undisputed in cancer cells, non-enzymatic scaffolding roles for large complexes of all KDM6 members have been recognized." (PMID 34950587, 2021). "Searching the Cancer Cell Line Encyclopedia (CCLE) we found significantly lower levels of expression of several histone demethylases (KDMs), including KDM6A and KDM6B, in SMARCA4def compared with MYCamp cells or with LC cells that are wild type for SMARCA4 and MYC." (PMID 34262032, 2021). "Currently, the increasing trend of documents showed the essential contribution of histone demethylases such as JARID1, KDM4, LSD1, KDM6B, KDM6A, KMD3, KDM5, and Jumonji domain–consisting of protein 6 (JMJD6) to the cancer stem cell phenotype in several kinds of cancers." (PMID 32280305, 2020). "We noticed that some of the SE-associated genes repressed by GSK-J4 treatment are well-known critical regulators of cancer cell stemness, such as ID126, 27 and TERT28, and further confirmed their downregulation by GSK-J4 or shRNAs targeting KDM6A or KDM6B in two CRC cell lines." (PMID 32929331, 2020). "Some pre-clinical studies already used the KDM6B inhibitors, GSKJ1/GSKJ4, to target cancers." (PMID 34991274, 2018). "All these studies therefore clearly indicated that KDM6B could be classified as an oncogene and was correlated to EMT and cancer aggressiveness." (PMID 34991274, 2018). "We also know that cancer cells present a very variable genotype and that EZH2 and KDM6B could drive a specific cell phenotype depending on the cellular context." (PMID 34991274, 2018). "Whether H3K27 demethylases including KDM6A, KDM6B and KDM7A play an oncogenic or anti-oncogenic role in cancers is under active investigation." (PMID 28717873, 2018). "Among the genes studied, the chromatin modifier KDM6B stood out in that it demonstrated a consistently significant positive effect size in the thyroid (0.46, SKAT-O FDR = 2%, in ASE), our GTex-discovery tissue, and in the TCGA-matched cancer type THCA (0.98, SKAT-O FDR = 0.5%, in ASE)." (PMID 41023738, 2025). "The other tissues and cancer types, while not significant with SKAT-O, usually exhibited a similar positive trend, suggesting this KDM6B association with NMD efficiency may not be thyroid-specific but likely impacts other tissues as well." (PMID 41023738, 2025). "KDM6B is upregulated via nuclear factor-κB (NF-κB) binding to its promotor region by tumor necrosis factor α (TNFα), and that KDM6B in turn upregulates mitogen-activated protein kinase (MAPK) pathway, thereby promoting cancer cell growth and survival in a catalytically-independent manner." (PMID 34950587, 2021). "Additionally, several studies suggested that both KDM3A and KDM6B were putative therapeutic targets in different cancer models, not including ESCC." (PMID 33318475, 2020). "However, the effect of KDM6B on tumorigenesis is not consistent among different human cancers." (PMID 28947976, 2017). "As a result, we observed significant enrichment of KDM6B on promoter regions of SOX2 and CD44 but not on SOX9 in detached cancer cells." (PMID 35186918, 2022). "However, to our knowledge, no studies targeted the common regulation of EZH2 and KDM6B during EMT and cancer." (PMID 34991274, 2018).